EPCAM (epithelial cell adhesion molecule)
Diseases named in the same sentence as EPCAM in open-access papers (continued):
Sharing a sentence is not in itself a finding about the gene and the disease.
colorectal cancer (continued). "The prognostic value of EpCAM-positive CTCs has been confirmed for further tumor entities, including lung cancer, advanced ovarian cancer, gastric cancer, colorectal cancer, and head and neck squamous cell carcinoma (HNSCC)." (PMID 32507912, 2020). "In line with this, the EpCAM+/EMMPRIN+ MV levels correlated with tumor size in colorectal cancer patients and decreased after surgical removal of the tumor." (PMID 32731639, 2020). "The CAR NK-92 cells specifically recognized EpCAM-positive colorectal cancer cells, released cytokines including IFN-γ, perforin, and granzyme B, and showed cytotoxic activity in vitro." (PMID 33101285, 2020). "In colorectal cancers, a therapeutic approach targeting EpCAM+ cells with aptamers has been performed in pre-clinical conditions." (PMID 32849491, 2020). "EpCAM-specific antibody Panorex® (edrecolomab; 17-1A) first attained market approval for treating colorectal carcinomas in 1995." (PMID 32507912, 2020). "EpCAM (epithelial cell adhesion molecule) was discovered four decades ago as a tumor antigen on colorectal carcinomas." (PMID 32507912, 2020). "In our previous study, we demonstrated that 89% of CTC isolated from colorectal cancer patients expressed EpCAM, despite CellSearch® being able to detect only a very small fraction." (PMID 31636732, 2019). "In this work, we have prepared a β-elemene and PTX-coloaded microemulsion anchored with SYL3C aptamer, which is capable of targeting the EpCAM over-expressed colorectal cancer cells and enhancing the anti-colorectal treatment." (PMID 31524012, 2019). "It was shown that low doses of the α-amanitin-conjugated anti-epithelial cell adhesion molecule (EpCAM) antibody lead to complete tumor regression in mouse models of human colorectal cancer with hemizygous deletion of POLR2A." (PMID 31398954, 2019). "Since miR-16-5p, miR-23a-3p, miR-23b-3p, miR-27a-3p, miR-27b-3p, miR-30b-5p, miR-30c-5p, and miR-222-3p are high in EpCAM+ colorectal cancer (CoCa) TEX, an EpCAM-dependent recruitment is discussed." (PMID 31921628, 2019). "In clinical study, CTCs were identified in all 7 patients with advanced colorectal cancer by epithelial cell adhesion molecule (EpCAM) staining." (PMID 31354892, 2019). "Stem cell surface markers like CD133, CD44, or EpCam have been used to enrich colorectal cancer TICs and to reflect their tumor-initiating properties." (PMID 30763370, 2019). "The transmembrane glycoprotein epithelial cell adhesion molecule (EpCAM), highly expressed in epithelial cancers, is a popular biomarker for the diagnosis, treatment, and imaging of epithelial-derived tumors such as colorectal cancer." (PMID 31524012, 2019). "EpCAM appears in 85% of colorectal carcinomas, it can inhibit differentiation and promote proliferation, and it is used to isolate CTCs in liquid biopsies." (PMID 31285270, 2019). "Our results demonstrated that combination with regorafenib can enhance the therapeutic efficacy of the EpCAM-specific CAR-NK-92 cells on colorectal cancer." (PMID 30410941, 2018). "Our results showed that the CAR-modified NK-92 cells can specifically kill EpCAM-positive colorectal cancer cells." (PMID 30410941, 2018). "The CAR-NK-92 cells can specifically recognize EpCAM-positive colorectal cancer cells and release cytokines, including IFN-γ, perforin, and granzyme B, and show specific cytotoxicity in vitro." (PMID 30410941, 2018). "Human colorectal carcinoma-associated GA733 antigen, also termed epithelial cell adhesion molecule (EpCAM), is selectively expressed in human colorectal carcinoma." (PMID 29773994, 2018). "In this report, we show that EpCAM-aptamer-guided survivin RNAi effectively downregulated survivin both in colorectal cancer cells in vitro and in a mouse xenograft model for colorectal cancer." (PMID 28724889, 2017). "In conclusion, EpCAM aptamer-guided delivery of survivin siRNA is able to target both the bulk and cancer stem cells in a xenograft colorectal cancer model." (PMID 28724889, 2017).
colorectal cancer (continued). "Here we describe the use of the EpCAM aptamer in delivering siRNA to target survivin expression in order to eliminate colorectal cancer stem cells." (PMID 28724889, 2017). "CART cells were generated with lentiviral transduction and exhibited specific in vitro killing activity against EpCAM-positive human ovarian and colorectal cancer cells." (PMID 28088790, 2017). "The ability of recombinant EpCAM BiTE protein to activate PBMC‐derived T cells was evaluated by adding unstimulated human primary CD3+ cells to a culture of human DLD colorectal carcinoma cells, which are known to express EpCAM on their surface." (PMID 28634161, 2017). "EpCAM was first described in 1979 as an antigen, which induced the production of specific antibodies after the immunization of mice with human colorectal carcinoma cells and the subsequent fusion of splenocytes with myeloma cells to create hybridomas." (PMID 28531111, 2017). "Previous studies indicated that low expression of EpCAM correlated with a tumour-promoting role and poor patient survival in colorectal cancer." (PMID 27009809, 2016). "Double immunohistochemical staining was used to detect the expression of EpCAM/CD44 in 80 cases of colorectal cancer and their corresponding liver metastases." (PMID 24765173, 2014). "Breast, prostate and colorectal cancers of epithelial origin carry a shared cell surface marker known as Epithelial Cell Adhesion Molecule or EpCAM." (PMID 24811334, 2014). "EPCAM deletion carriers will probably be more easily recognized than carriers of an MSH6 mutation, whose colorectal cancer risk is lower with a higher age of onset." (PMID 23938213, 2013). "In one study B lymphocytes from a patient with colorectal cancer treated with a mouse mAb, specific for the epithelial-cell adhesion molecule (Ep-CAM), were immortalized with Epstein–Barr virus to isolate anti-idiotypic antibodies." (PMID 23162790, 2012). "Colorectal cancers show the most frequent EpCAM expression of all human adenocarcinoma analyzed to date with 99.7% of primary tumor samples (N = 1,186 CRC patients) being positive." (PMID 20976159, 2010). "In this study, it was shown that treatment with monoclonal rat anti-mouse EpCAM antibody G8.8 induced proliferation of mouse and human lung carcinoma cells as well as human colorectal carcinoma cells." (PMID 19002182, 2008). "C4.4A expression was compared with the expression of EpCAM, galectin-3 and CO-029, which have been described as reliable markers in colorectal cancer." (PMID 17912244, 2007). "Accordingly, in liver metastasis of colorectal cancer, the sensitivity of EpCAM and CO-029 also was significantly higher than for C4.4A (P=0.04 and 0.02, respectively)." (PMID 17912244, 2007). "Moreover, EpCAM+ CTCs from colorectal cancer have been reported to fuse with macrophages to form CD45+ circulating hybrid cells, which exhibited increased tumor heterogeneity and metastatic behavior." (PMID 40525275, 2025). "The functional characterization of Epithelial Cell Adhesion Molecule (EpCAM) in colorectal cancer (CRC) progression has been constrained by methodological limitations, particularly the potential for truncated protein isoforms to confound traditional genetic knockout approaches." (PMID 41357552, 2025). "SYL3C is capable of targeting EpCAM, which is overexpressed in colorectal cancer cells." (PMID 38675202, 2024). "The inhibitory effect of EpCAM-CAR-T on colorectal cancer in vivo was detected using xenografts." (PMID 39107717, 2024). "In summary, the study demonstrates the selective killing effect of EpCAM-specific CAR-NK-92 cells on colorectal cancer cells in vitro and highlights the potent combination therapy of CAR-NK-92 cells and regorafenib in suppressing tumor growth in a humanized CRC mouse model." (PMID 38694508, 2024).
colorectal cancer (continued). "This method entails coating magnetic GZCIS/ZnS QDs with mesoporous silica, loading epirubicin into the pores, capping with Au NPs, PEGylation, and conjugating with epithelial cell adhesion molecule (EpCAM) aptamers to actively target colorectal cancer (CRC) cells." (PMID 38561432, 2024). "In cancer cells, EpCAM has proven to be a stem cell marker and maintains and promotes cell stemness in a range of cancers, including hepatocellular carcinoma, nasopharyngeal carcinoma, non-small-cell lung cancer, colorectal cancer, and gastric cancer." (PMID 38791091, 2024). "Notably, over 97% of colorectal cancer patients exhibit elevated expression of epithelial cellular adhesion molecules (EpCAM), contributing to cell proliferation and metastasis." (PMID 38694508, 2024). "Indeed, several of the compounds reduced EpCAM-mediated cyclin D1 (CCND1) expression in colorectal carcinoma cell line HCT-8; however, they have yet to be tested against tumor growth." (PMID 38612911, 2024). "A CD3(scFv)/EGFR(Nb)/EpCAM(Nb) trispecific T-cell engager (TriTE) was developed to target colorectal cancer cells that could activate T cells and lyse colorectal cancer cells." (PMID 36761751, 2023). "However, studies in gastric cancer, clear renal cell carcinoma, colorectal cancer, and non-small cell lung cancer have reported a direct correlation between increased EpCAM expression and an overall better prognosis of patients." (PMID 37627911, 2023). "For example, anti-EpCAM nanobody-based TriKEs could be developed for stimulating NK cells’ cytotoxicity in colorectal cancer using EpCAM-specific nanobodies." (PMID 36761751, 2023). "Therefore, EpCAM was chosen as additional tumor target in combination with CEA since both TAAs are known to be co-expressed on colorectal cancer cells." (PMID 38169746, 2023). "The biological role of EpCAM has been proved in most solid tumors, including colorectal cancer." (PMID 35016698, 2022). "For example, numerous preclinical studies have confirmed the efficacy of CAR-NK cells upon CXCL12/SDF-1α secreting glioblastoma and epithelial cell adhesion molecule (EpCAM) positive colorectal cancer cells in xenograft model by targeting EGFRvIII via intravenous infusion." (PMID 35303962, 2022). "It has been reported that the epithelial cell adhesion molecule (EpCAM) could be used as a marker to isolate epithelial-derived EVs from the blood sample of colorectal cancer patients by immunoaffinity-capture." (PMID 35784717, 2022). "Moreover, fluorescent images of HT-29 and NIH/3T3 cells further confirmed the specificity of the EpCAM aptamer for targeting HT-29 colorectal cancer cells." (PMID 36686226, 2022). "We next examined whether recEpMab-37 could recognize endogenous EpCAM in colorectal carcinoma Caco-2 cells." (PMID 35735360, 2022). "In 1979, EpCAM was discovered as a tumor antigen expressed on colorectal carcinoma cells." (PMID 35517503, 2022). "Additionally, the killing efficacy of EpCAM CAR T cells against EpCAM-positive colorectal cancer cells was positively correlated with the E:T ratio." (PMID 34790117, 2021). "In addition, combination therapy with regorafenib and EpCAM-directed CAR-NK92 cells resulted in a superior anti-tumor effect against colorectal cancer than monotherapy of either treatment." (PMID 34072732, 2021). "Furthermore, EpCAM was upregulated in human colorectal cancers and formed a complex with claudin-7 in primary tumors and metastases." (PMID 34209658, 2021). "Accordingly, low EpCAM expression was observed in melanoma, some neurological cancers, lymphomas, and sarcomas, while high EpCAM expression was observed in breast, gallbladder, gastric, pancreatic, prostate, and colorectal cancers." (PMID 34209658, 2021).
colorectal cancer (continued). "The isolation of circulating tumour cells (CTCs) in colorectal cancer (CRC) mostly relies on the expression of epithelial markers such as EpCAM, and phenotypic characterisation is usually performed under fluorescence microscopy with only one or two additional markers." (PMID 34945008, 2021). "However, the incidence of CTCs in NSCLC was reportedly lower than that in other cancers such as prostate, breast, ovarian, and colorectal cancer, as determined using the EpCAM-dependent method." (PMID 33747909, 2021). "We found that cancer antigen- EpCAM expression increased in the metastatic stage compared with the primary stage in cancers and the activation of Wnt and TGFβ pathways was positively correlated with EpCAM expression in multiple cancers, including colorectal cancer." (PMID 34790117, 2021). "In addition, epithelial cell adhesion molecule (EpCAM) was reported to promote colorectal cancer (CRC) metastasis and recurrence." (PMID 34345203, 2021). "In this study, the expression of HLA-G (n=157), ILT-2/4 (n=82), and PD-L1 (n=70) in epithelial cell adhesion molecule (EpCAM)-positive colorectal cancer (CRC) cells was analyzed by multicolor flow cytometry, and the prognostic significance of these molecules was evaluated." (PMID 34054869, 2021). "The EpCAM antigen is also found in other cancers such as lung or colorectal carcinoma." (PMID 34590615, 2021). "Epithelial cell adhesion molecule (EpCAM) is a type-1 transmembrane glycoprotein that was first discovered 40 years ago from monoclonal antibody screening against antigens derived from colorectal cancer cells." (PMID 32046162, 2020). "Indeed, EpCAM-positive exosomes were harvested from the serum and/or the plasma of lung, ovarian and colorectal cancer patients using an anti-EpCAM antibody to establish novel cancer diagnostic methods 53-55." (PMID 32226524, 2020). "In addition, blood plasma of colorectal cancer and lung cancer patients have a higher level of EpCAM+ exosome as compared to the blood plasma of their respective healthy controls." (PMID 32046162, 2020). "Many TAA and tumor-specific antigens have been used as target structures for the development of colorectal cancer therapies or vaccines such as melanoma associated antigen (MAGE), vascular endothelial growth factor receptor 1 and 2 (VEGFR-1 and VEGFR-2), EpCAM and EGFR." (PMID 32707982, 2020). "The EpCAM is a cell-surface glycoprotein highly expressed in colorectal carcinomas." (PMID 33143243, 2020). "Additionally, the cytotoxicity of CAR-NK-92 cells against EpCAM-positive colorectal cancer cells was positively correlated with the E : T ratios." (PMID 30410941, 2018). "However, another study from Li group displayed the anti-tumor activity of TINCR in colorectal cancer, wherein loss of TINCR expression promoted proliferation, metastasis through activating EpCAM cleavage." (PMID 29614984, 2018). "Thus, EpCAM aptamer-guided RNAi of survivin enhanced the 5-FU-mediated cell death in colorectal cancer cells via enhanced apoptosis." (PMID 28724889, 2017). "However, in colorectal cancer, the loss of TINCR expression promotes proliferation and metastasis by activating EpCAM cleavage." (PMID 28738804, 2017). "In colorectal cancers 80-100% overexpression of EpCAM is found." (PMID 27842504, 2016). "Previously we reported that LIM1863 colorectal cancer (CRC) cells secrete three distinct extracellular vesicle subtypes – two subpopulations of exosomes (apical EpCAM-Exos and basolateral A33-Exos) and shed microvesicles (sMVs) – with distinct protein and miRNA signatures." (PMID 27917920, 2016).
colorectal cancer (continued). "Notably, proteomic analysis of exosomes released from colorectal cancer cells has identified the presence of EpCAM on those microvesicles, and in bladder cancer, urinary soluble EpCAM levels were detected and increased with stage and grade of the tumor." (PMID 25477371, 2015). "CD133 has also been used as a marker for colorectal carcinoma stem cells, whereas other studies demonstrated that such cells could be identified by expression of either EpCAM or CD44 or a combination of EpCAM, CD44 and CD166 or ALDH1." (PMID 26703575, 2015). "In colorectal cancer EpCAM appears to act as molecule with protective function, since EpCAM deletions result in a higher risk to develop cancer and overexpression of EpCAM in colorectal cancer cells has been shown to inhibit metastasis and invasion of tumor xenografts in mice." (PMID 23758908, 2013). "In light of the recent discovery of tumor-initiating cancer stem cells (CSCs) in various tumor types, we developed an in vitro CSC model from xenograft tumors established in mice from a colorectal cancer patient tumor in which the CD133+/EpCAM+ population represented tumor-initiating cells." (PMID 23826249, 2013). "The EpCAM promoter was chosen as it has been regulated by the EpCAM protein which was shown earlier that it is over expressed in many primary tumors (Head & Neck cancer, Gastric cancer, Colorectal cancer) including retinoblastoma." (PMID 24391761, 2013). "Likewise, colorectal carcinomas present a high and constant expression of EpCAM, reaching recovery rates of up to 80% and making EpCAM-based immunoenrichment the method of choice." (PMID 22304365, 2012). "This compares well with EpCAM and CO-029 expression in over 90% of colorectal cancer." (PMID 17912244, 2007). "90% of Colorectal carcinoma cells express EpCAM but in a differential form." (PMID 17325709, 2007). "Moreover, EpCAM-specific antibodies were first approved for treating colorectal cancer in 1995." (PMID 39911266, 2025). "The epithelial cell adhesion molecule (EpCAM) is a transmembrane glycoprotein that is constitutively expressed in epithelial tissues and frequently overexpressed in epithelial-derived malignancies, including lung carcinoma, colorectal cancer, and pancreatic cancers." (PMID 41417221, 2025). "Our group previously developed a neutralizing antibody against EpCAM, EpAb2-6, which has strong potential for use as a colorectal carcinoma (CRC) treatment." (PMID 37543570, 2023). "Additionally, the overexpression of epithelial cell adhesion molecule (EpCAM), a 40-kDa glycoprotein expressed in 85% of colorectal carcinoma was reported to enhance the proliferative and invasive capacities of tumors and can inhibit differentiation and promote proliferation." (PMID 33499047, 2021). "We aimed to comprehensively investigate the clinicopathologic and molecular implications of altered epithelial cell adhesion molecule (EPCAM) expression in colorectal carcinoma (CRC)." (PMID 26528695, 2016). "Beyond MUC1 and EpCAM, the nucleolin-binding aptamer AS1411 has also been extensively applied in colorectal cancer nanomedicine." (PMID 41560835, 2026).